IL2 (interleukin 2)
Diseases named in the same sentence as IL2 in open-access papers (continued):
Sharing a sentence is not in itself a finding about the gene and the disease.
tumor (continued). "Furthermore, IL-2, IL-12, IFN-γ and TNF-α have been reported to stimulate CD4+ Th1 differentiation and accelerate Th1-mediated antitumor responses; In addition, these cytokines stimulate CD8+ cytotoxic T lymphocytes (CTLs), the most important effector cells that recognize and eliminate tumor cells." (PMID 37048096, 2023). "However, given the absence of lymphocyte stimulators and the state of the tumor, conditioning PBLs with IL-2 and CD28 may further augment the cytotoxic potential of T cells with anti-PDL1-BiTE." (PMID 39282109, 2023). "With a recently published report of MEOX1 being important for the acquisition of a tumor-infiltrating Treg cell phenotype it is conceivable to speculate, that MEOX1 in humans is a key factor for the transcriptional acquisition of a Treg cell effector phenotype downstream of IL-2 signaling." (PMID 37559728, 2023). "Taken together, our results suggest that Ce6-PDT has local antitumor activity, and its immune response, through the production of pro-inflammatory (Th1) cytokines such as TNF-α, IFN-γ, and IL-2, might restrict tumor growth on the non-irradiated right flank of the mice due to the abscopal effect." (PMID 36835310, 2023). "We had previously reported CD25 Mab, an afucosylated, IL-2 non-blocking human IgG1 antibody, that was shown to efficiently deplete Tregs in humans and solid tumor bearing mice, while allowing binding of IL-2 to effector T cells and the formation of anti-tumor adaptive immune responses." (PMID 37205201, 2023). "Indeed, the infusion ex vivo 70-kDa heat shock protein (Hsp70)/IL-2-activated NK cells together with the anti-PD-1 antibody was shown to be highly effective in local tumor control as well as improving the infiltration of CD8+ cytotoxic lymphocytes and NK1.1+ cells in the tumor bed." (PMID 37298470, 2023). "Additionally, low dose (LD) IL-2 treatment preferentially saturates IL-2Rα (CD25), which is highly expressed on regulatory T cells (Tregs), over IL-2Rβ/γ, which is expressed on CD8+ T cells and NK cells; this paradoxically decreases anti-tumor immunity due to Treg activation." (PMID 36911698, 2023). "Similarly, intracavitary IL-2 administration resulted in an increase in peripheral CD8 T cells expressing granzyme B and in peripheral NK cell activity, and intracavitary administration of an adenovirus/interferon β construct resulted in increased peripheral NK activity and anti-tumor antibodies." (PMID 35222439, 2022). "Their an mechanisim may be that they can promote the proliferation of T lymphocytes, secrete the cytokine interleukin-2, inhibits the secretion of interleukin-8, downregulates the protein expression of VEGF and MMP-9, restrain the formation of new blood vessels, and control tumor cell adhesion." (PMID 36438813, 2022). "Moreover, mice that showed complete responses following treatment with TransCon TLR7/8 Agonist and IL-2 did not develop palpable tumors following tumor rechallenge, indicating immunological memory developed with the combination treatment during the initial tumor challenge." (PMID 36123697, 2022). "Increasing IL-2 signaling has been postulated as a possible therapy for UC/CMML patients since it may increase Treg populations and increase NK cell activity, leading to increased protection of colonic mucosa in UC and increased cytotoxicity directed to tumor cells in CMML." (PMID 35228982, 2022). "Some years ago, a mutated IL-2 (termed no-alpha mutein) was developed which has a disrupted affinity for the high affinity IL-2R, expands preferentially CD8+ T lymphocytes and NK cells over Tregs and exerts a higher anti-metastatic effect than IL-2 in 3LL-D122 and B16 tumor models." (PMID 36569901, 2022). "Sequential use of GM-CSF and IL-2 after chemotherapy could enhance the antigen-presenting function of dendritic cells, promote stronger and more effective immunological activity of antigen-specific CTL, and improve the positive development of tumor immunity and the reconstruction of immune function." (PMID 36387089, 2022).
tumor (continued). "However, there is evidence suggests that IL-2 may preferentially expand CD4+ regulatory T (Treg) cells rather than tumor-killing CD8+ cytotoxic T cells (CTLs)." (PMID 35432319, 2022). "However, IL-2–induced, T-bethi Tc1 cells have a short lifespan in the suppressive tumor microenvironment (TME) after ACT, and our previous studies showed that adoptively transferred tumor-specific Tc9 cells elicit a stronger antitumor response against advanced tumors than Tc1 cells." (PMID 35192544, 2022). "Therefore, it seems that overexpression of IL-2 does not enhance the abscopal effect of combined tumor treatment using calcium electroporation and bleomycin electrotransfer; however, it has a significant inhibitory effect on the growth of directly treated tumors." (PMID 35954434, 2022). "Consequently, the downregulated c-Myc fails to regulate IL-2/12-stimulated NK cell metabolic reprogramming (including the upregulation of glycolysis) and thus impairs NK cells’ antitumor capacity, which perpetuates tumor progression." (PMID 36003368, 2022). "Since the IL2 supplemented media is not sufficient to activate naïve T-cells and IL2 receptor expression is restricted to antigen-activated T-cells, the results suggest that these activated T-cells were already specific to an antigen in the tumour microenvironment." (PMID 35158816, 2022). "Furthermore, IFN-γ/IL-2 profile of cytokine production (without TNF-α) could be ascribed to regulatory T cells that suppress the anti-tumor functions of CD4 +, CD8 +, and NK cells, leading to an absence of effective anti-tumor immune response." (PMID 34199989, 2021). "After in vitro expansion via anti-CD3-mediated T cell activation in the presence of high doses of IL-2 and reinfusion in tumor-bearing mice, these TILs demonstrated a 50- to 100-fold higher therapeutic potency compared with lymphocyte cultures that were not derived from the tumor." (PMID 34571883, 2021). "We hypothesized that a tumor associated antigen and CD3-targeting bispecific antibody, rather than targeting to only γδ TCR, would enhance the anti-tumor effects of the transfused Vγ2Vδ2 T cells even without administration of phosphoantiens and IL2 into the animals." (PMID 34040604, 2021). "However, following ex vivo stimulation with SIINFEKL peptide IFN-γ, TNF-α nor IL-2 production was increased in combination treated mice spleen but not tumor compartment, suggesting that antigen-specific CD4 T cells reside prevalently in secondary lymphoid organ." (PMID 34276686, 2021). "In addition, the relevance of combining NK cell infusion and inhibitory receptor blockade is reinforced by our preclinical mouse model data, which demonstrated the potent antitumor role of IL-2 NK infusion when inhibitory receptors are not engaged by tumor targets." (PMID 34071607, 2021). "Therefore, our results indicate that the tumor homing ability of macrophages may not be affected by phagocytosis of PODS or by the embedded IL-2 cargo protein." (PMID 37849947, 2021). "Thus, if the treatment does not yield a reduction in tumor size shortly after the start of treatment, it may be advantageous to administer an IL-2 immunotherapy in combination with the OVT and anti-PD-1, in order to increase the T cell proliferation rate." (PMID 34771476, 2021). "Moreover, the mRNA expression levels of IFN-γ and IL-2 in tumor tissues in the DTSP-treated group were increased, which further supports the hypothesis that the activated Th1 immune response contributes to the Anti-Tumor effect." (PMID 32903495, 2020). "However, blocking IL-2 restored Th17 responses and tumour formation after Tregs depletion, indicating that Tregs restrain the availability of IL-2 in the local microenvironment, allowing the development of the Th17 cells necessary to promote ETBF-triggered neoplasia." (PMID 32680511, 2020).
tumor (continued). "Also, treatment of CXCL9 could dose-dependently reduced the mRNA expression and secretion of anti-tumour cytokines from CD8+ cytotoxic T cells, including TNFα, IL2, and IFNγ, further proving that CXCL9 treatment could lead to cytotoxic T cell exhaustion and dysfunction." (PMID 31913856, 2020). "Interestingly, the DC maturation marker CD83 was significantly more expressed in wt OAd and OAd.TNFa-IL2-treated tumors as well as KO OAd.TNFa.IL2-treated tumors, indicating that virus-induced AIM2-mediated tumor-cell signaling might play a role in DC activation." (PMID 32225009, 2020). "In addition, we hypothesized that procalcitonin would be lower as the immune response would be directed to the radiated tumor and not manifest systemically as is the case with high-dose IL-2." (PMID 32467299, 2020). "Moreover, the different MoCM IL-2 concentrations did not correlate with tumor cells viability." (PMID 33312693, 2020). "In addition, such an IL-2 analog could be expected to synergize with anti-CTLA-4 and anti-PD-1 CPI therapy and/or vaccination through numerical expansion and further activation of tumor-specific Teff subsets." (PMID 32005826, 2020). "The functions of IL-2 therapy are known to directly activate CTLs in lymphoid and nonlymphoid tissues, but it is not yet clear whether the preexisting T cells inside the tumor are sufficient for the effectiveness of IL-2 therapy." (PMID 31462678, 2019). "The adoptively transferred NK cells persisted from one week to several months, but the persistent NK cells expressed significantly lower levels of NK group 2-member D (NKG2D, an activating receptor) and could not lyse tumor cells in vitro unless they were reactivated with IL-2." (PMID 31614472, 2019). "Besides, DC cells activated with CD137 could not only secrete IL-2 and IL-6 to promote the proliferation of T cells but also activate cytotoxic lymphocytes (CTLs) and promote the secretion of IFN, hereby enhancing the anti-tumor effect." (PMID 31708918, 2019). "Accordingly, in an immunocompetent tumor microenvironment, IL-12/15/18 pre-activated NK cells might be superior in competing for low amounts of IL-2 with CD25+ regulatory T cells, which restrain IL-2–dependent expansion of NK cells and T cells after adoptive cell transfer." (PMID 30546366, 2018). "Because of the activation of Treg cells in the tumor, IL2 treated patients paradoxically may not necessarily show improved efficacy, even though there is a profound increase in the number of cytotoxic T cells at the tumor site." (PMID 29467958, 2018). "In addition, and importantly, we observed survival of G3-EGFRvIII CAR T-cells within the tumor as long as 90 days after implantation after a low-dose treatment and single administration without any need for ongoing IL-2 supplementation, accompanied by a marked tumor stroma demolition." (PMID 29975720, 2018). "Likewise, when the flank tumor was allowed to grow for 7 days rather than 4 days prior to AIT treatment, the IL-2, IL-21, IL-2/21, IL-7/15 and IL-7/15/21 groups all had significant slowing of tumor growth or tumor regression when compared to the control or cyclophosphamide-alone groups (p < 0.03)." (PMID 28146052, 2017). "Thus we feel the SELECT trial may not have used optimal selection and the result from this trial should not discourage further exploration and utilisation of tumour pathology as predictive biomarker in HD IL2." (PMID 27777776, 2016). "The presence of tumor-conditioned medium increased production of IL-2 by spleen cells from the control mice and from the vaccinated mice almost two-fold, while IL-2 production by the spleen cells from the mock-vaccinated tumor-bearing mice was not significantly affected by the conditioned medium." (PMID 27598146, 2016).
tumor (continued). "However intracellular cytokine staining of splenic CD4+ T cells from mice in which tumor escape had occurred indicated an increased rather than decreased proportion of IL-2+ T cells in the presence of tumor-specific B cells, with the majority of T cells co-expressing TNF." (PMID 27121060, 2016). "However, before the development of multiple TKIs, interleukin-2(IL-2) and interferon-alfa(IFN-a) based immunotherapy is the only treatment that has been shown to improve survival in metastatic RCC(mRCC), which emphasizes the importance of host immunity in anti-tumor treatments." (PMID 27661105, 2016). "Additionally, this reduction in tumor size could not be reproduced with either IL-10 or IL-2 expressing tumors alone." (PMID 26217588, 2015). "In addition, differences in the preparation of the tumor cell suspensions, i.e. TIL obtained after enzymatic digestion or after 1-2 weeks culture of tumor fragments in high dose IL-2 for the aAPC and REM expansion platforms respectively, may also be of influence." (PMID 23402380, 2013). "Thus, when anti-IL-2Rα MAbs are employed in the unique host environment that exists after therapeutic TMZ-induced lymphodepletion, vaccine-stimulated anti-tumor T-cells may be independent of IL-2 signaling whereas TRegs will remain dependent." (PMID 22383993, 2012). "Interestingly, we also observed correlations between pathways (IL12, IFNG, IL2) involved in Th1 mediated immune response, as well as correlations between pathways (IL13, TGFB) that act via Th2 immune responses to putatively suppress the tumor inhibitory role of Th1 pathways." (PMID 21050467, 2010). "Our findings support the hypothesis that LB tumour cell proliferation is mediated by an autocrine pathway involving endogenous IL-2 generation, despite the fact that these cells are not dependent on exogenous IL-2 to grow in culture." (PMID 9083328, 1997). "As it has been suggested that an autocrine mechanism may control tumour cell growth, in this work cells from a spontaneous murine T lymphocyte leukaemia (LB) expressing the interleukin-2 receptor (IL-2R) (CD25) were evaluated in vitro for IL-2-mediated autocrine growth." (PMID 9083328, 1997). "In addition, in the N592 model, IL-2-producing N592 inhibited the growth of wild-type N592 injected at the same site, while injection of parental cells on the opposite side did not significantly affect the growth of wild-type tumour cells." (PMID 8795583, 1996). "Five cytokines—IFN‐γ, TNF‐α, GM‐CSF, IL‐2, and IL‐15—were detected only in the CSF of MUE cases and not in IE or neoplasia cases." (PMID 40859633, 2025). "This design efficiently bridges T cells and tumor cells, triggering immune synapse formation and cytotoxic activity without requiring co-stimulatory signals like CD28 or IL-2." (PMID 39982231, 2025). "At these lower doses, systemically administered immunotherapies, be they ICIs, bispecific antibodies, or immune-stimulating cytokines, such as interleukin-2 (IL-2) or interferon-alpha (IFN-α), are unlikely to reach optimal concentrations within a tumor." (PMID 40868739, 2025). "In comparison, TIGIT mAb-treated mice exhibit higher frequencies of tumour-infiltrating CD8+ T cells expressing IL2/TNF-α/IFN-γ and CD4+ T cells expressing IL2, without altering the ratio of memory CD4+ T cells." (PMID 40994140, 2025). "Compared with CD19R+ T cells, CD19RCD28+ T cells exhibited superior proliferation without exogenous IL-2, produced IL-2, propagated efficiently, and upregulated the anti-apoptotic protein Bcl-XL after CD19+ tumor cell stimulation." (PMID 40699780, 2025). "GzB-IL18-armored T cells produced significantly more IL2 in response to CD3+CD28 crosslinking, but not tumor cells." (PMID 38745414, 2024). "T lymphocytes or T killer cells from either healthy or tumor-bearing dogs can be successfully expanded and activated ex vivo, with the aid of anti-CD3 antibody, IL-2, with or without other cytokines such as interferon α (IFN-α)." (PMID 38668417, 2024).
tumor (continued). "In a murine melanoma tumor model, NKTR-214 resulted in a CD8+ T cell to Foxp3+ Treg cell ratio greater than 400, compared to 18 for non-PEGylated IL-2." (PMID 39169031, 2024). "No IL-2 and IFN-γ secretion was detected in cultures of T cells alone, tumor cells alone, or when irrelevant target cells like PANC-1 were involved." (PMID 38425341, 2024). "This IL-2 receptor targeting liposomes, and not free IL-2, allowed specific and repeated targeting, and expansion of ACT-T cells in B16F10 tumor-bearing mice." (PMID 39030582, 2024). "TCR135-engineered CD8+ T cells were also activated by C666-1-EBNA1 tumor cells and expressed higher levels of IFN-γ, IL-2, and TNF-α than non-transduced TCRneg-CD8 T cells." (PMID 38412034, 2024). "Actually, periphery CD16-CD56 + bright/dim NK cells do not start with anti-tumor activity, but can rapidly proliferate and transform into CD16CD56+bright NK cells after stimulation by cytokines (IL-2, IL-12 and IL-15) to acquire anti-tumor cytotoxic capacity." (PMID 38245747, 2024). "CD8+ T cells from WT mice were transduced with either anti-hB7-H3 CAR or anti-hB7-H3 CAR expressing an shRNA against Adam17, and adoptively transferred into tumor-bearing mice with MC38 expressing hB7-H3, without additional IL-2/sumIL-2 treatment." (PMID 38918390, 2024). "In line, analysis of culture supernatants by Legendplex assays showed a significant increase in IL-2, IFNγ, IL-10 and TNF secretion after treatment with 1 nM CC-3, but not with the isotype control or when target antigen negative tumor cells were used." (PMID 37122707, 2023). "Studies show that the majority of the anti-tumor CD8+ T cells are in the exhausted state, and do not express interleukin-2 (IL-2) or tumor necrosis factor α (TNF-α)." (PMID 37415732, 2023). "In all groups where electrotransfer of plasmids IL-2 (EP1 pIL-2), IL-12 (EP1 pIL-12), and their combination (EP1 COMB) was performed, a delay in tumour growth was observed compared to control groups (without treatment and treatment with EP or plasmids only)." (PMID 37629081, 2023). "In comparison, when mice received supportive IL-2, and Non-Td, CoStAR-Td, or TCR-Td T cells, mice reached their tumor volume limits by days 52, 76, and 55, respectively." (PMID 38022678, 2023). "Tumor engrafted NSG mice were treated with either PBS or Non-Td, TCR-Td, CoStAR-Td or TCR.CoStAR-Td cells at the 5x106 dose in the absence of IL-2 support." (PMID 38022678, 2023). "The levels of anti-tumor immune-response-related factors (interferon-γ (IFN-γ), interleukin-10 (IL-10), tumor necrosis factor- α (TNF-α) and IL-2) were evaluated in patients with negative and positive expressions of INHBA." (PMID 36984496, 2023). "When LCMV-primed T cells and tumor cells were co-incubated, 5-NL increased the expression of TNF alpha (TNFα), GZMB and IL-2 in CD8+ T cells incubated with B16.GP33 but not B16 cells." (PMID 37582744, 2023). "Transduction of a CTLA-4:CD28 CSR into tumor-specific T cells, resulted in elevated IFN-γ and IL-2 production and enhanced antitumor effect without systemic autoimmunity." (PMID 35432319, 2022). "Based on the dynamic results for these four cytokines, like TNF-α, IL-2, IL-6 and IFN-γ were secreted at higher levels in the high tumor burden group than in the low tumor burden group, but the differences were not obvious." (PMID 35013456, 2022). "Most importantly, the altered DC subset distribution in the tumor is likely to account for reduced Pmel-1 activation, since the mice that underwent TBI without IL-2 treatment showed the highest frequency of cDC1 and the lowest frequency of MoDC." (PMID 36497152, 2022). "In contrast, correlations between DKK1 and cytokines mainly deriving from or acting on lymphocytes such as IL2, IL4, or IL17 were weaker or absent in tumor tissues." (PMID 36539532, 2022).